TUBB6 (tubulin beta 6 class V)
Diseases named in the same sentence as TUBB6 in open-access papers:
TUBB6 is named in the same sentence as 58 diseases in open-access papers, as found by Europe PMC text mining. Sharing a sentence is not in itself a finding about the gene and the disease. The quoted sentences say what the papers report.
breast cancer (5 papers, 2012 to 2025). A primary or metastatic malignant neoplasm involving the breast. "Recently, expression of tubulin genes, TUBB3 and TUBB6, was significantly downregulated in the taxane-resistant breast cancers." (PMID 35677170, 2022). "Of these, six genes (ABAT, DEPDC1, KIF2C, SMAD4A, TAF1D, and TUBB6) have been reported to be directly relevant to cancer mechanisms, such as mammary tumor progression (P = 0.046)." (PMID 23185353, 2012).
glioma (5 papers, 2020 to 2026). A benign or malignant brain and spinal cord tumor that arises from glial cells (astrocytes, oligodendrocytes, ependymal cells). "ROC curves of 1-, 3-, and 5-years survival rates of glioma patients show the accuracy of TUBB6 in the prognostic prediction of glioma patients." (PMID 33193654, 2020). "In this research, we found that TUBB6 is significantly related to glioma grades and poor prognosis, indicating that TUBB6 may play an important role in glioma genesis and development process." (PMID 32406502, 2020). "There were one, five and four studies showing a statistically significant increase in the mRNA expression level of TUBB6, RAB5, and SLC25A22 in brain and CNS cancer tissues, in comparison with normal tissues." (PMID 33193654, 2020). "Only TUBB6 was listed among the top 1% in GENE RANK of brain and CNS cancer, and we selected TUBB6 as the key prognostic gene for the following analysis." (PMID 33193654, 2020). "The key prognostic gene TUBB6 (Tubulin Beta 6 Class V) is mapped on chr18:12,307,669-12,344,320 and is listed among the top 1% in GENE RANK of brain and CNS cancer." (PMID 33193654, 2020). "Most of them were reported in glioma, CACNG2 JPH3, TUBB6, NRSN1, FAM19A2, NALCN, GNAL have not been reported yet." (PMID 32406502, 2020). "CACNG2, JPH3, TUBB6, NRSN1, FAM19A2, NALCN, GNAL have not been reported in gliomas." (PMID 32406502, 2020). "In addition, there is no report about CACNG2, JPH3, TUBB6 (tubulin β 6 class V), NRSN1, FAM19A2, NALCN, CDH18, GNAL on glioma." (PMID 32406502, 2020). "In addition, CACNG2, JPH3, TUBB6, NRSN1, FAM19A2, NALCN, GNAL were not reported in glioma." (PMID 32406502, 2020).
colorectal cancer (4 papers, 2018 to 2021). A primary or metastatic malignant neoplasm that affects the colon or rectum. "Tubulin beta 6 class V (TUBB6) was recognized as a potential mutation hot spot in human colorectal cancers accompanied by microsatellite instability 39 and serves as a biomarker for predicting GC peritoneal metastasis." (PMID 32174791, 2020). "As for miRNA-targeted genes in COAD, TUBB6, FZD3, and SERPINE1 were reported to be prognostic biomarkers in colorectal cancer potentially." (PMID 32964043, 2020).
gastric cancer (4 papers, 2015 to 2024). A primary or metastatic malignant neoplasm involving the stomach. "Few studies have focused on the biological functions of PRICKLE2, PDE12, RBP1, THSD7B, and TUBB6 in gastric cancer." (PMID 36226177, 2022). "TUBB6 is used as a prognostic biomarker in many cancers, such as gastric cancer, ovarian cancer, prostate cancer and triple-negative breast cancer." (PMID 33193654, 2020).
bladder cancer (3 papers, 2023 to 2025). "A recent evidence indicated that high expression of TUBB6 was linked to a poor prognosis of patients with bladder cancer, and knockdown of TUBB6 significantly inhibited cell migration and invasion." (PMID 38023248, 2023). "Inhibition of TUBB6 could significantly reduce cell migration and invasion ability by suppressing cell cycle progression in bladder cancer." (PMID 40083923, 2025).
Duchenne muscular dystrophy (3 papers, 2019 to 2024). Duchenne muscular dystrophy (DMD) is a neuromuscular disease characterized by rapidly progressive muscle weakness and wasting due to degeneration of skeletal, smooth and cardiac muscle. "Tubb6 exhibited the highest degree of upregulation with a ∼4-fold increase upon PE treatment; this is notable as Tubb6 induction has been causally implicated in microtubule network reorganization in Duchenne Muscular Dystrophy." (PMID 35433678, 2022). "Overexpression of the TUBB6 gene disrupts microtubule networks in muscle fibers of Duchenne Muscular Dystrophy mouse models, analogous to pathologies observed in mdx mice, indicating its pivotal role in microtubule organization." (PMID 39766789, 2024).
glioblastoma (3 papers, 2020 to 2026). The most malignant astrocytic tumor (WHO grade IV). "Increased TUBB6 gene expression is associated with decreased OS in patients with primary glioblastoma." (PMID 40867242, 2025).
prostate carcinoma (3 papers, 2014 to 2021). A carcinoma that arises from epithelial cells of the prostate gland. "TUBB6 was previously proposed as a prognostic biomarker in several cancer types including gastric, ovarian and prostate cancer." (PMID 34885088, 2021). "In the results, two of the four genes (TUBB6, PARM1) are supported by literature for their roles in prostate cancer; nonetheless, the other two (SLC25A22, MYEF2) are less known." (PMID 25151146, 2014).
astrocytoma (2 papers, 2025 to 2026). "Analysis of the SHAP values for the remaining genes revealed that increased expression of ZDHHC18, HDAC1, and TUBB6 enhances the probability of predicting astrocytoma, while elevated expression of TERT, TRIM67, NOG, KCNIP2, and KCNJ11 increases the probability of predicting oligodendroglioma." (PMID 40867242, 2025).
dysplasia (2 papers, 2018 to 2019). A usually neoplastic transformation of the cell, associated with altered architectural tissue patterns. "Further study of TUBB6 by tissue group demonstrated a significant (ANOVA P = 0.0043, F = 3.81) progression in methylation from normal mucosa, where methylation was at its lowest, through acute inflammation to dysplasia and neoplasia where methylation was as its highest." (PMID 29762666, 2018). "Methylation in the beta-tubulin TUBB6 correlated with the presence of dysplasia (P < 0.0001) and accurately discriminated between dysplasia and nondysplastic tissue, even in the apparently normal field mucosa downstream from dysplastic lesions (AUC 0.84, 95% CI 0.81–0.87)." (PMID 29762666, 2018).
gastric tumor (2 papers, 2023). "Among autophagy genes in the Reactome database, PRMT1 was negatively correlated with genes such as ATG9A, DYNC1H1, EPAS1, PINK1, TSC1, TUBB6, and ULK1 in gastric tumor tissues (STAD-TCGA) and positively correlated with HMMR, ESCO2, CHAC2, and NUDT6 (STAD-TCGA)." (PMID 37564212, 2023).
lung carcinoma (2 papers, 2013 to 2021). "To further validate these novel players in lung cancer cell migration, we selected five candidates—DSE, CPA4, FLNC, TUBB6, and BICC1—and the positive control CDH2, which were upregulated in fast cells and also associated with poor overall survival in NSCLC patients." (PMID 33934493, 2021).
non-small cell lung carcinoma (2 papers, 2024 to 2025). A group of at least three distinct histological types of lung cancer, including non-small cell squamous cell carcinoma, adenocarcinoma, and large cell carcinoma. "Additionally, TUBB6 was found to be a migration control factor in non-small cell lung cancer, which posed a negative correlation with patient survival." (PMID 40083923, 2025).
ovarian carcinoma (2 papers, 2020 to 2021). A malignant neoplasm originating from the surface ovarian epithelium. "Unsurprisingly, decreased TUBB6 expression was significantly associated with increased overall survival in five independent ovarian cancer cohorts (GSE9891, GSE30161, GSE3149, GSE13876 and GSE49997) in OSov." (PMID 35053021, 2021).
acute coronary syndrome (1 paper, 2019). Signs and symptoms related to acute ischemia of the myocardium secondary to coronary artery disease. "Most genes were associated with multiple drugs, for example, TUBB6 was targeted by 12 unique compounds with diverse therapeutic indications such as oncology and acute coronary syndrome." (PMID 31217489, 2019).
Anxiety (1 paper, 2021). Intense feelings of nervousness, tension, or panic often arise in response to interpersonal stresses. "The results showed that Gfap, Rhog, Gnai2, Ppp1r1b, and Uqcrh were specifically dysregulated in the prefrontal cortex of the depression-susceptible group, while Tubb6, Urod, Cul1, Spred1, and Gpcpd1 were specifically dysregulated in the anxiety-susceptible group." (PMID 33627638, 2021).
brain tumors (1 paper, 2022). "Tubb6 (tubulin, beta 6 class V) is a member of the beta tubulin superfamily, which is linked to skeletal muscle, osteoclast function and brain tumors in previous studies." (PMID 35346355, 2022).
gastritis (1 paper, 2015). Inflammation of the stomach. "In addition, gene TUBB6 is mutated in primary cancer, accompanied by highly expressed TUBB6 mRNA in both primary cancer and metastatic cancer relatively to gastritis tissue (Fold change > 6)." (PMID 26330360, 2015).
head and neck squamous cell carcinoma (1 paper, 2020). A squamous cell carcinoma that arises from any of the following anatomic sites: lip and oral cavity, nasal cavity, paranasal sinuses, pharynx, larynx, and salivary glands. "TUBB6 in HNSC (head and neck squamous cell carcinoma) was significantly correlated with ten immune-infiltrating cells, such as CD8 + T cells (p-value = 1.42E-07)." (PMID 33193654, 2020).
hepatocellular carcinoma (1 paper, 2024). A malignant tumor that arises from hepatocytes. "Moreover, TUBB6 was published to promote the hypermethylation of CpG islands in the promoter region of tumor-related genes in GC, hepatocellular carcinoma, and high-grade serous ovarian carcinoma 50-52." (PMID 38706908, 2024).
neovascular age-related macular degeneration (1 paper, 2025). "The RNA expression profiles of endothelial cells (ECs) from proliferative diabetic retinopathy (PDR) patients and neovascular age-related macular degeneration (nAMD) patients also exhibited an elevation in TUBB6." (PMID 40083923, 2025).
pituitary adenomas (1 paper, 2018). "Likewise, TUBB6B (tubulin beta 6 class V) was significantly downregulated in AIPmut negative non-functioning pituitary adenomas (NFPAs, −8.4-fold change, P = 0.0057 vs. normal pituitary)." (PMID 29507682, 2018).
proliferative diabetic retinopathy (1 paper, 2025). Advanced retinopathy due to diabetes mellitus characterized by the formation of new vessels in the retina. "Bioinformatics analysis of publicly available transcriptomic datasets (GEO accession: GSE94019, 29) demonstrated a notable elevation of TUBB6 expression in retinal microvascular ECs from patients with proliferative diabetic retinopathy (PDR) in contrast to normal subjects." (PMID 40083923, 2025).
ptosis (1 paper, 2024). The drooping of the upper eyelid. "We identified a TUBB6 p.(Glu410Lys) variant in syndromic familial ptosis pedigree ENG_CML; this substitution has been reported as P/LP for tubulinopathies in four paralogs (TUBB2A, TUBB2B, TUBB3, and TUBB4A; ClinVar Variation IDs: 986830, 1195195, 6967, 135658)." (PMID 38585811, 2024).
steatosis (1 paper, 2022). Increased lipid within the cytoplasm of cells. "Furthermore, the expression levels of CYP1A1, NOCT, and TUBB6 were regulated, indicating the effects of improving the antioxidant capacity of liver tissues, reducing the steatosis of hepatocytes, and inhibiting the inflammatory reaction of hepatocytes, respectively." (PMID 35408620, 2022).
ulcerative colitis (1 paper, 2021). An inflammatory bowel disease involving the mucosal surface of the large intestine and rectum. "Curiously, some of the genes highlighted here, such as TOMM40 and TUBB6, were associated not only with neurodegenerative diseases, like Alzheimer’s, but also with ulcerative colitis." (PMID 33936067, 2021).
cancer (18 papers, 2010 to 2025). A tumor composed of atypical neoplastic, often pleomorphic cells that invade other tissues. "Based on the density of local network regions, we predicted CHMP7, NPR2, and TUBB6 as novel pathogenic genes whose splice variants impact the interaction network similarly as splice variants of cancer-associated genes." (PMID 32879328, 2020). "For instance, in a study using 60 cancer cell lines with different invasion abilities, TUBB6 is identified as an invasion-associated (IA) gene." (PMID 25151146, 2014). "TUBB6 has been linked to cancer invasion and metastasis in aggressive malignancies." (PMID 38601640, 2024). "TUBB6 was significantly correlated with stromal score in 18 cancer types and with immune score in 17 cancer types." (PMID 33193654, 2020). "This study aimed to assess the importance of novel hub genes by analyzing the expression, potential function and prognostic impact of TUBB6 in human primary GBM cancer." (PMID 33193654, 2020). "TUBB6 in ten cancer types was correlated with M0 macrophages, especially in LGG (p-value = 4.92E-06)." (PMID 33193654, 2020). "β-Tubulin, of which TUBB6 is a subtype, plays a prominent role in cell survival, allowing cancer cells to survive, and these cell survival pathways can also be responsible for resistance to chemotherapy." (PMID 28800781, 2017). "Many years of research revealed the intricate relationship between TUBB6 and malignant tumors." (PMID 38706908, 2024). "Next, the heatmap is visually analyzed the correlation of TUBB6 co-expressed genes in pan-cancer." (PMID 33193654, 2020). "Moreover, studies have also indicated that TUBB6 itself is functionally related with the metastasis of various cancers." (PMID 25151146, 2014). "Furthermore, a subsequent analysis on the possible role of the altered genes in CRC and IPD data sets in the survival of cancer patients (TCGA-COAD data sets) pointed to a significant influence on survival for eight of these genes (TUBB6, PAK6, SULT1A1, SLC11A1, TRAP1, FAM50B, SPON2, FES)." (PMID 34885088, 2021). "Among the previously found cancer-hallmark survival-related genes (PAK6, SLC11A1, SULT1A1 and TUBB6), we observed that their differential expression still had a significant impact on survival for three of the genes (PAK6, SLC11A1 and TUBB6), when considering stage stratification." (PMID 34885088, 2021). "As for TUBB6 and MTHFD2, two and seven unique analyses of data with statistical significance revealed higher expression levels in cancer tissues than in normal tissues." (PMID 33193654, 2020). "Exon skipping in genes such as TUBB6, FGFR1, cAMP-dependent protein kinase inhibitor gamma (PKIG), and METTL5 was observed, which could lead to the development of cancer or affect a normal function of nervous system." (PMID 40395612, 2024).
tumor (12 papers, 2017 to 2025). "According to the expression level estimated by qRT-PCR (n = 32), the gene TUBB6 was selected as our target gene which exhibited the highest relative expression in tumor tissues and demonstrated an obvious correlation with the bad survival prognosis." (PMID 38706908, 2024). "More specific, ADM, NDRG1, and TUBB6 were down-regulated, while other 10 genes were up-regulated in tumor samples compared with normal control." (PMID 33344235, 2020). "In our own analysis of colitis associated mucosa utilising the Illumina Methylation450 platform, we identified an association between hypomethylation of TUBB6 in non-neoplastic colonic mucosa from patients with UC associated neoplasia." (PMID 30473377, 2019). "Sodium bisulfite sequencing (BSP) was used to validate the 6 randomly selected candidate islands, in which the results of 5 mapped genes (ANKRD45, CDX1, APC, HOXD3 and TUBB6) showed significant differences in the 10 pairs of validation tumor and adjacent tissue cohorts." (PMID 28418032, 2017). "In our risk model, the expression of five genes (PODN, NPY, MICU3, TUBB6 and RHOJ) was decreased in tumor tissues, and the greater the degree of downregulation was, the better the prognosis was, indicating that the hypermethylation of these genes may play a protective role in GC patients." (PMID 32174791, 2020). "We found that taxane-resistant tumor showed elevated expression levels of TUBB1 and lower expression levels of TUBB3, TUBB4B, and TUBB6 genes when compared with the sensitive tumors." (PMID 30126203, 2018). "We found that tumor tissues express significantly higher levels of TUBB and TUBB3 and significantly lower levels of TUBB2B, TUBB6, and TUBB7P pseudogene." (PMID 30126203, 2018). "Analyzing expression profile of BC tumors and tumor-adjacent normal breast tissues showed upregulation of TUBA1A, TUBA1C, TUBB and TUBB3 and downregulation of TUBB2A, TUBB2B, TUBB6, TUBB7P pseudogene, and TUBGCP2 in the tumor tissues compared to the normal breast tissues." (PMID 30126203, 2018).
kidney diseases (1 paper, 2024). "This suggests that TUBB6 may be used as a potential biomarker to compare two related kidney diseases (FSGS and MCD), and TUBB6, RPL27, and PFDN5 can be used as potential biomarkers to detect FSGS." (PMID 39519211, 2024).
TUBB6 also shares sentences with these, for which no sentence is quoted: oligodendroglioma (2 papers); adenocarcinoma (1); breast tumors (1); choroidal neovascularization (1); Chronic colitis (1); chronic gastritis (1); clear cell renal cell carcinoma (1); colon cancer (1); colorectal tumor (1); depression (1); dystrophinopathy (1); E. coli infection (1); focal segmental glomerulosclerosis (1); glomerulosclerosis (1); ischemic stroke (1); metastatic cancer (1); muscular dystrophy (1); Myalgia (1); myotonic dystrophy (1); neurodegenerative disease (1); neurological disorders (1); proliferative retinopathy (1); renal carcinoma (1); Salmonella Infections (1); serous ovarian carcinoma (1); toxoplasmosis (1); triple-negative breast carcinoma (1); tubulinopathies (1); viral myocarditis (1).